APOE (apolipoprotein E)
Diseases named in the same sentence as APOE in open-access papers (continued):
Sharing a sentence is not in itself a finding about the gene and the disease.
Alzheimer disease (continued). "The relationship between Apolipoprotein E (ApoE) and the aggregation processes of the amyloid β (Aβ) peptide has been shown to be crucial for Alzheimer's disease (AD)." (PMID 20140182, 2010). "While much has been written about the role of APOE in Alzheimer Disease, the overall profile of APOE across diseases places it as being similar to periodontal disease." (PMID 19208189, 2009). "Essential to defining how apoE influences the memory disruption and etiology of neurodegenerative disorders such as Alzheimer's disease is the establishment of the role of apoE in synaptic function." (PMID 19725929, 2009). "Studies on the genetic basis of cognitive decline and Alzheimer's Disease (AD) have pointed out Apolipoprotein E (APOE), a protein intimately involved in synaptogenesis but also numerous neuropathological processes, as an important marker." (PMID 19698138, 2009). "Examples in Alzheimer's disease (AD) include apolipoprotein E (apoE), especially its E4 isoform, α1-antichymotrypsin, and C1q complement factor." (PMID 19090993, 2008). "APOE is the prime candidate for late-onset Alzheimer's disease and patients are routinely screened for these APOE genotypes." (PMID 18628954, 2008). "As they age, untreated ApoE null mice develop cognitive deficits that resemble Alzheimer's disease in addition to profound atherosclerotic pathogenesis." (PMID 18823563, 2008). "SorLA has been shown to be down regulated in Alzheimer's disease brains, interact with ApoE, and modulate Aβ production." (PMID 16930450, 2006). "Understanding of the more common late-onset Alzheimer disease (LOAD), is centered on the role of one universally accepted risk gene, the apolipoprotein E locus (APOE)." (PMID 16515697, 2006). "Dr. Sheffield argues that some DNA analysis like HFE (hemochromatosis) and APOE (Alzheimer Disease) testing is potentially harmful." (PMID 16756678, 2006). "The apolipoprotein E (APOE) and tau proteins play important roles in the pathological development of Alzheimer's disease (AD)." (PMID 16603077, 2006). "There are other examples of genes having such pleiotropic effects, the most notable being APOE in hyperlipidemia and Alzheimer's disease." (PMID 15752431, 2005). "Some of the issues that are likely to face alcohol researchers once they identify susceptibility genes can be illustrated using the example of Alzheimer’s disease (AD) and the apolipoprotein E (ApoE) gene." (PMID 12875045, 2002). "Notably, the protective effects of klotho appear most pronounced in individuals with high genetic or pathological risks, such as apolipoprotein E ε4 carriers in Alzheimer's disease." (PMID 41983942, 2026). "It seems noteworthy therefore that protein products of major APOE gene variants differ in their numbers of cysteines capable of forming disulfide dimers, with the allele (ε4) associated with highest rates of Alzheimer's disease (AD) possessing none." (PMID 41858499, 2026). "The Ser82 allele was found to be significantly more frequent in AD patients than in controls, particularly among individuals lacking the APOE ε4 allele, suggesting an independent association with Alzheimer’s disease risk." (PMID 40981102, 2025). "Alzheimer’s disease is perhaps one of the most known conditions that has strong ApoE involvement." (PMID 40149482, 2025). "The effects of sex and apolipoprotein E (APOE)—Alzheimer's disease (AD) risk factors—on white matter microstructure are not well characterized." (PMID 39711105, 2025). "In conclusion, we found that three genes (APOE, PICALM, and TSPOAP1) associated with Alzheimer’s disease in EA are also associated with the measure of cognitive functions in South Asians living in India, with the association primarily driven by missense/LoF SNVs." (PMID 40565532, 2025). "In conclusion, higher PA is associated with lower Alzheimer’s disease risk, independent of polygenic and APOE-derived genetic risk." (PMID 41329349, 2025).
Alzheimer disease (continued). "Overall, this in-silico analysis enhances our understanding of how ApoE nsSNPs L122P may influence Aβ pathology and the progression of Alzheimer’s disease." (PMID 40892789, 2025). "This study employed an integrated in silico framework to systematically identify and evaluate potentially deleterious non-synonymous SNPs (nsSNPs) in the human ApoE gene, focusing on their structural, functional, and pathological relevance to Alzheimer’s disease (AD)." (PMID 40892789, 2025). "Two studies examined the combined risk of Alzheimer’s disease linked to HSV1 and the APOE-ε4 gene." (PMID 40573903, 2025). "Furthermore, the APOE-ε4 gene, a critical factor in Alzheimer’s disease, is often more highly expressed in females, making them more susceptible." (PMID 40604656, 2025). "Previous research on ApoE largely focused on the fields of cardiovascular and Alzheimer's disease, and it influences a wide range of common cellular processes (e.g., neuroinflammation, degradation, and clearance of amyloid beta, synaptogenesis, membrane repair and remodeling, and neuronal growth)." (PMID 40495209, 2025). "A proposed model outlines how the development of Alzheimer’s disease in APOE ε4 carriers occurs." (PMID 41303587, 2025). "Second, further investigations are encouraged to achieve a better and more reliable prediction performance by combining MRI-derived features (e.g. structural and functional MRI) and other modality data (e.g. APOE genotype, Alzheimer’s disease pathology derived from blood and CSF)." (PMID 39963290, 2025). "Amnestic multi-domain MCI with positive AD biomarkers and APOE ε4 homozygosity carries a very high short-term risk of conversion to AD dementia, whereas non-amnestic single-domain MCI is more likely to remain stable or to evolve toward non-Alzheimer dementias." (PMID 41562827, 2025). "The mechanisms underlying the protective effect of the e2 variant of the APOE gene (APOEe2) against Alzheimer’s disease (AD) have not been elucidated." (PMID 40026419, 2025). "The consideration of the σ2-R/PGRMC1 complex as a key regulator of Aβ1-42 oligomer and apoE accumulation in the cell has led to the conclusion that it may be of clinical significance in the treatment of Alzheimer’s disease." (PMID 40732235, 2025). "This study demonstrated that APOE ε4, the most significant genetic risk factor for Alzheimer's disease and also a risk factor for IHD, worsens lipid and lipoprotein profiles (e.g., APOE ε4 is associated with elevated LDL-C, lower HDL—C, elevated ApoB, and lower ApoA-I)." (PMID 41282305, 2025). "Other studies have shown a potential role of a late-onset Alzheimer’s disease-derived polygenic risk score in predicting EOAD cases, though differences in age of participants and APOE status may confound direct comparisons." (PMID 39825484, 2025). "AEP and LRP‐1 both influence the regulation of the extracellular matrix, Aβ deposition, and apolipoprotein E (ApoE) synergy, which indicates that these two proteins may exist in the crosslink between vascular disease and Alzheimer's disease." (PMID 40116141, 2025). "Rising HDL-cholesterol levels are also associated with functional harm for APOE-ε4 non-carriers with Alzheimer’s disease, probably because of reduced lipid availability to protect neuronal membranes." (PMID 40834163, 2025). "Compared to individuals with no chronic pain or SCP, those with MCP exhibited higher Aβ in regions most vulnerable to Alzheimer’s disease pathology—including the entorhinal cortex, hippocampus and inferior temporal cortex—with levels further amplified by APOE-ɛ4 load and age." (PMID 40496670, 2025). "In conclusion, our study provides evidence of a significant association between leukocyte telomere shortening and Alzheimer’s disease, independent of traditional cardiovascular risk factors and APOE ε4 genotype." (PMID 40303469, 2025).
Alzheimer disease (continued). "Overall, our results provide new insights into the roles of ApoE during HSV1 infections which may inspire future studies on Alzheimer’s disease etiology." (PMID 40295730, 2025). "It is unclear whether the different Alzheimer's disease (AD) progression trajectories of apolipoprotein E (APOE) ɛ4 carriers is reflected by blood phosphorylated tau (p‐tau) analytes." (PMID 41451854, 2025). "The mild phenotype differences observed in some studies may reflect early effects of Alzheimer’s disease–related pathology in apolipoprotein E ε4 carriers." (PMID 39896129, 2025). "On the other hand, connectivity is regulated in a complex way by the main players in the pathogenesis of Alzheimer’s disease (Aβ, tau, neuroinflammation and APOE genotype), and may provide a common biological substrate for the interactions of these markers." (PMID 39741782, 2025). "When underexpressed, NR1H2 increases cellular cholesterol ­levels and amyloidogenesis by downregulating the apolipoprotein E.14Specifically, the T allele of rs2695121 (NR1H2) may affect the risk of Alzheimer’s disease and produce higher behavioral burden." (PMID 40834163, 2025). "In addition to its primary role in amyloid generation and deposition, apolipoprotein E also influences tau protein pathology, neurodegeneration, and the microglial response in Alzheimer’s disease." (PMID 41516203, 2025). "The significant effect modification by genetic background, particularly the APOE genotype in Alzheimer’s disease interventions, further complicates the establishment of universal recommendations and highlights the need for stratified approaches in future research." (PMID 41515400, 2025). "Genes involved in cholesterol metabolism, such as APOE, CLU, and ATP‐binding cassette transporters, including apolipoprotein E, apolipoprotein J, and ATP‐binding cassette transporters, are linked to the pathophysiology of Alzheimer's disease." (PMID 41277170, 2025). "Although the association of the APOC1 genotype with disease risk may partly result from linkage disequilibrium with APOE, independent associations between APOC1 genotype and Alzheimer’s disease have been observed in various ethnic groups." (PMID 40722932, 2025). "A 2023 prospective longitudinal study showed that MHT was associated with smaller changes towards Alzheimer’s disease pathophysiology than non-therapy and that APOE ε4 carrier status was linked to an amplified treatment outcome." (PMID 40439116, 2025). "Apolipoprotein E (APOE- gene; apoE- protein) is a multifunctional protein involved in lipid transport, neuroinflammation, and neuronal repair, playing a crucial role in brain physiology and the pathogenesis of Alzheimer’s disease (AD)." (PMID 40275327, 2025). "Factors predicting more rapid progression to dementia include being diagnosed with amnestic or multi-domain MCI, having biomarkers of Alzheimer’s disease (AD) such as higher amyloid burden, apolipoprotein E (APOE) ε4 carrier status and comorbid frailty and depression." (PMID 39833003, 2025). "Analyses were carried out following stratification of the sample by established dementia Alzheimer's disease (AD) risk factors including sex and presence or absence of the apolipoprotein E (APOE) ε4 allele." (PMID 40221237, 2025). "Enhancing apoE lipidation could also provide a new intervention strategy for late-onset Alzheimer’s disease, specifically for APOE4 carriers, because apoE4 is less lipidated than apoE2 or apoE36,69." (PMID 38824138, 2024). "The analyses also identified individuals who had a family history of Alzheimer's disease and individuals who were APOE ε4 carriers as having a decreased odds of trial dropout of 25% and 21% respectively; though these associations were only marginally significant." (PMID 39044496, 2024).
Alzheimer disease (continued). "It is also unclear whether the apolipoprotein E (APOE) epsilon 4 (ε4) polymorphism, which confers greater genetic susceptibility for late-onset Alzheimer’s disease, is associated with greater TBI-related cognitive decline." (PMID 39036434, 2024). "In addition, APOE E is suggested to affect selenium uptake via trapping LRP8 in late-onset Alzheimer disease." (PMID 38908072, 2024). "Because sleep apnea and disordered breathing have been indicated in earlier onset of Alzheimer’s disease, as well as cognitive impairment, this work will serve as a foundation for researching downstream effects of hypoxia and hypoxic-hypercapnia in APOE genotype and sex." (PMID 38748407, 2024). "A major problem to clarify the role of APOE in Alzheimer’s disease specifically and to define a therapeutic hypothesis to support a translational approach, is the pleiotropic function of APOE." (PMID 39528861, 2024). "In the early phase of Alzheimer’s disease, astrocytes are the primary source of APOE in the brain." (PMID 39528861, 2024). "APOE is a well-known gene for dyslipidemia and Alzheimer’s disease." (PMID 39858587, 2024). "The APOE E4 allele is associated with an increased risk of developing Alzheimer’s disease (OR = 2–3 in heterozygosis; OR = 14.9 in homozygosis), although the presence of the APOE E4 allele is not necessary or sufficient to develop Alzheimer’s disease." (PMID 39200345, 2024). "APOE’s interaction with amyloid β (Aβ) is crucial in Alzheimer’s disease pathogenesis." (PMID 38790930, 2024). "Additionally, future studies should consider including information on amyloid-beta deposition and APOE genotyping, as these were important biomarkers of Alzheimer’s disease." (PMID 38642314, 2024). "For example, FH may regulate or inhibit the mTOR pathway, and binds to apolipoprotein E (apoE), a major protein related to Alzheimer’s disease." (PMID 38799460, 2024). "Patients that carry the apoE ε4 allele have higher risk for developing Alzheimer’s disease than non-carriers." (PMID 38312931, 2024). "According to previous sequencing studies in Alzheimer’s disease, apolipoprotein E (Apoe) was suggested to downregulate TGF-β in microglia, but whether this applies to other disease contexts is unknown." (PMID 38869957, 2024). "Though NODDI has shown promise in studies of normal ageing, early-onset Alzheimer’s disease, and other tauopathies, there is currently insufficient data to draw conclusions about the influence of APOE ɛ4 on grey matter NODDI measurements in cognitively normal midlife adults." (PMID 38384997, 2024). "Regional brain expression of several Alzheimer-risk genes, including APOE, CD33, and SORL1, showed a strong correlation with brain metabolism, particularly in regions of the brain that are affected earliest and most severely in Alzheimer’s disease." (PMID 38469573, 2024). "The study showed that those who have the APOE ε4 gene were more likely to have Alzheimer’s disease." (PMID 39698202, 2024). "Furthermore, apolipoprotein E (APOE) and amyloid, which play a key role in the pathogenesis of Alzheimer’s disease, were also found in the fibrillar material of PXS." (PMID 38790964, 2024). "Due to these factors, we chose to examine APOE mRNA levels in Alzheimer’s disease-affected brains." (PMID 38674351, 2024). "Studies have shown CSF proteome changes similar to Alzheimer's disease during chemotherapy, including increases in Apolipoprotein E (APOE) and Calsyntenin-1 (CLSTN1), and decreases in Sodium/potassium-transporting ATPase subunit alpha-3 (ATP1A3), linked to several neurological disorders." (PMID 38350915, 2024). "Covarying for age, sex and APOE ɛ;4 status, atypical Alzheimer’s disease participants had decreased pDMN and vDMN connectivity and increased adDMN connectivity relative to CU individuals, at P < 0.05 with family-wise error (FWE) correction for multiple comparisons." (PMID 38444909, 2024).
Alzheimer disease (continued). "Thus, we compared the disease and gene information through the example of Alzheimer’s disease and APOE as the search criteria." (PMID 38632621, 2024). "Currently, there are several major biological hypotheses regarding gender differences in Alzheimer’s disease, including age-related decreases in sex hormones (estrogen, progesterone, testosterone), various genetic risks (ApoE, Etc)." (PMID 39162899, 2024). "Taken together, this review highlights the complex interaction of apolipoprotein E, the triggering receptor on myeloid cells 2, and transforming growth factor-β as part of a regulatory axis in microglia at the onset and over the course of Alzheimer’s disease." (PMID 38542077, 2024). "We analyzed data from two independent cohorts, including 732 participants from the Hallym University Medical Center and 483 from the Alzheimer’s Disease Neuroimaging Initiative, each group consisting of individuals with and without the APOE ε4 allele." (PMID 39114318, 2024). "In addition, another study showed that LDL-C is similarly unrelated to APOE genotypes in the pathophysiology of Alzheimer’s disease." (PMID 39363901, 2024). "Our finding on the statistical significance of APOE ε4 for the cognitive frailty phenotype is consistent with the published data on its involvement in cognitive impairment, particularly neurodegenerative diseases such as Alzheimer's disease." (PMID 38300644, 2024). "Furthermore, amid the increasing range of genetic risk factors that have been identified, the Apolipoprotein E (APOE) gene is highlighted as the strongest and most prevalent, influencing over fifty percent of all instances of Alzheimer’s disease (AD)." (PMID 39654135, 2024). "Another important finding of this study was that higher AD-PRS scores were associated with greater atrophy over time in Alzheimer's disease-vulnerable regions, including the hippocampus, independent of APOE-ɛ4 status." (PMID 39229494, 2024). "Apolipoprotein E (APOE) carries of subjects converted to Alzheimer’s disease (AD)." (PMID 38894849, 2024). "The Apolipoprotein E (APOE) gene has been established in the Alzheimer’s disease (AD) literature to impact brain structure and function and may also show congruent effects in healthy older adults, although findings in this population are much less consistent." (PMID 38635499, 2024). "In models including PRS and APOE-ε4 status, a higher global PRS (β = 1.91, t-value = 11.01, p < 0.001) and number of APOE-ε4 alleles (β = 0.94, t-value = 8.60, p < 0.001) were significantly associated with an Alzheimer’s dementia diagnosis." (PMID 36909609, 2023). "TOMM40 ‘523 has been associated with cognitive performance and risk for developing Alzheimer’s disease independent of the effect of APOE genotype." (PMID 37718796, 2023). "This work presents an overview of how brain-derived and peripheral ApoE ε4 might be involved in blood–brain barrier breakdown and promote neurodegenerative processes possibly leading to Alzheimer’s disease." (PMID 37947590, 2023). "The task was administered to apolipoprotein (APOE) ε4 allele carriers, of whom almost half develop Alzheimer’s disease by the average age of 76, compared to only 20% of non-carriers who convert to Alzheimer’s disease by the average age of 84." (PMID 36595510, 2023). "The APOE locus has been associated with increased vulnerability to severe COVID-19 mortality, especially for the APOE4 homozygous genotype which is the strongest genetic risk factor for sporadic Alzheimer’s disease." (PMID 37240292, 2023). "Consistently, carriers of rs1151999-G, together with three other PPARG SNPs, were strongly protected against Alzheimer’s disease when they did not carry the ε4 allele of apolipoprotein E (APOE), indicating a gene–gene interaction." (PMID 37047733, 2023).